AXL (AXL receptor tyrosine kinase)
Diseases named in the same sentence as AXL in open-access papers (continued):
Sharing a sentence is not in itself a finding about the gene and the disease.
osteoarthritis (3 papers, 2017 to 2025). A noninflammatory degenerative joint disease occurring chiefly in older persons, characterized by degeneration of the articular cartilage, hypertrophy of bone at the margins and changes in the synovial membrane. "The optimal cut‐off value of serum AXL level was obtained by ROC curve as 33.375 ng/mL, which was used to distinguish healthy controls and all osteoarthritis (including KL 0 to IV)." (PMID 34841689, 2022). "The level of serum AXL in patients with osteoarthritis is significantly higher than in healthy controls, and is closely related to the severity of radiographic osteoarthritis." (PMID 34841689, 2022). "The level of serum AXL was significantly higher in the osteoarthritis group than that in the control group (P < .05)." (PMID 34841689, 2022). "In osteoarthritis, impaired efferocytosis and elevated levels of apoptotic cells have been observed in synovial tissues, which have been linked to the deficiency of membrane-bound TAM receptors (Tyro3, AXL, and MERTK)." (PMID 40458640, 2025).
osteoporosis (3 papers, 2022 to 2025). A condition of reduced bone mass, with decreased cortical thickness and a decrease in the number and size of the trabeculae of cancellous bone (but normal chemical composition), resulting in increased fracture incidence. "We speculated that the alleviation of osteoporosis is partially attributed to AXL/ERK5 pathway upregulation and the stimulation of osteogenic differentiation." (PMID 36408274, 2022). "The identification of ESR1, NRP2, AXL, ERBB2, and GAB1 as key genes provides novel therapeutic targets and highlights the importance of understanding shared molecular pathways in osteoporosis and sarcopenia." (PMID 40660573, 2025). "The 5 genes (AXL, GAB1, ERBB2, NRP2, and ESR1) along with 13 pharmacological agents represent promising candidates for enhancing the treatment of osteoporosis and sarcopenia." (PMID 40660573, 2025). "This study revealed that Mangiferin promotes osteogenic differentiation of MC3T3-E1 cells and alleviates osteoporosis in OVX mice, with AXL/ERK5 as a potential pathway." (PMID 36408274, 2022).
preeclampsia (3 papers, 2016 to 2025). Preeclampsia is a hypertensive disorder of pregnancy that is characterized by new-onset hypertension with proteinuria presenting after 20 weeks of gestation, and depending on mild or severe forms may initially present with severe headache, visual disturbances, and hyperreflexia. "AXL expression has been detected in the trophoblast, and perturbations in Gas6 signaling through AXL have been shown to be associated with preeclampsia, suggesting a possible mechanism of pathology." (PMID 27560129, 2016).
psoriasis (3 papers, 2017 to 2023). An autoimmune condition characterized by red, well-delineated plaques with silvery scales that are usually on the extensor surfaces and scalp. "In psoriasis subjects, AXL, CA-15-3 and SP-D were significantly downregulated by apremilast." (PMID 31953524, 2020).
rhabdomyosarcoma (3 papers, 2011 to 2023). A rare aggressive malignant mesenchymal neoplasm arising from skeletal muscle. "Because AXL is induced during resistance development to IGF-1R-targeted therapies in rhabdomyosarcomas, which may also be the case in ES, this further supports a rationale to target AXL in ES." (PMID 25528764, 2014). "Interestingly, AXL is also induced during acquired therapy resistance including against IGF-1R-targeted therapy in a rhabdomyosarcoma model." (PMID 25528764, 2014).
schwannoma (3 papers, 2014 to 2025). A benign, usually encapsulated slow growing tumor composed of Schwann cells. "In addition, GAS6-AXL signaling has recently been shown to increase Schwannoma cell matrix adhesion and survival, further arguing for an involvement of AXL in Schwann cell tumorigenesis." (PMID 25551830, 2014).
Sepsis (3 papers, 2020 to 2025). Sepsis is defined as life-threatening organ dysfunction caused by a dysregulated host response to infection. "Future studies should incorporate clinical patient samples to explore the regulatory effects of the GAS6/AXL signaling pathway in different sepsis conditions and conduct relevant clinical trials to assess its therapeutic potential." (PMID 40480981, 2025). "Although soluble AxL levels increase concurrently, believed to inhibit Gas6 activity by binding with it, the upregulation of Gas6 during sepsis exceeds that of sAxl." (PMID 38956732, 2024). "Additionally, while this study confirms the essential role of the GAS6/AXL pathway in microglia, its behavior in various sepsis models and human clinical samples requires further validation." (PMID 40480981, 2025). "However, the expression of AXL in the rat’s urine was decreased after sepsis." (PMID 32194432, 2020). "AXL, CDH16, PARK7, and PGLYRP2 were significantly changed in the urine of patients suffering from sepsis-induced AKI." (PMID 32194432, 2020). "Clinically, GAS6/AXL pathway activators or related drugs could offer a novel therapeutic strategy for treating SAE by enhancing microglia’s anti-inflammatory and clearance capabilities, potentially improving neurological outcomes in sepsis patients." (PMID 40480981, 2025).
squamous carcinoma (3 papers, 2019 to 2023). "The results showed that AXL and MIG6 expression were positively correlated in both the CCLE and the Lee lung datasets (p < 0.0001) and they both had higher expression levels in adenocarcinoma than in squamous carcinoma." (PMID 37834326, 2023).
Ureteral obstruction (3 papers, 2019 to 2024). Obstruction of the flow of urine through the ureter. "To determine the efficacy and underlying molecular mechanisms of AXL inhibition in CKD, we employed a murine unilateral ureteral obstruction (UUO) model preventively treated with a selective AXL kinase inhibitor (bemcentinib) during disease progression." (PMID 39559366, 2024). "The study aim was to investigate the role of AXL inhibition in kidney fibrosis due to unilateral ureteral obstruction (UUO)." (PMID 31134766, 2019). "Expression of EMT‐related markers was also found to be increased by ureteral obstruction, and AXL staining was detected in the intertubular interstitial cells, sporadically apical in the tubular epithelial cells of atrophic tubules and in parietal cells of the Bowman′s capsule in glomeruli." (PMID 31134766, 2019).
adenoma (2 papers, 2021). A neoplasm arising from the epithelium. "Avaliar o papel prognóstico dos biomarcadores CD133, AXL e c-MYC e sua associação com características clinicopatológicas de adenocarcinomas e adenomas colorretais." (PMID 33759958, 2021). "AXL expression was found only occasionally, and predominantly dominated in adenomas, with less penetrance in high-grade dysplasia." (PMID 33759958, 2021). "Microarranjos teciduais (TMA) dos tumores primários e adenomas foram realizados em busca de expressão de CD133, c-MYC e AXL, com posterior análise de relação significativa com características clinicopatológicas." (PMID 33759958, 2021). "In the univariate analysis, there was no statistical significance between CD133+, c-MYC+ and AXL+ adenomas and size, anatomic location, type, histological diagnosis and status of dysplasia." (PMID 33759958, 2021). "In the adenoma group, no statistically significant expression or correlation with patient outcome data were found for the biomarkers CD133, c-MYC and AXL." (PMID 33759958, 2021).
Ascites (2 papers, 2020 to 2023). Accumulation of fluid in the peritoneal cavity (between the layers of the peritoneum that lines the abdomen). "Furthermore, presence of ascites, hepatic encephalopathy, and infectious complications were associated with low numbers of CD68+AXL+ cells." (PMID 37004869, 2023).
astrocytoma (2 papers, 2012 to 2017). "An increased expression of GAS6 was associated with increased MERTK/AXL expression in astrocytoma patient samples." (PMID 28675785, 2017). "The same study indicates that the knockdown of AXL as well as MERTK by siRNA in the astrocytoma line G12 results in decreased AKT and ERK phosphorylations." (PMID 28675785, 2017). "Compared to EZH2, we found a stronger expression of AXL in astrocytoma grade II and III." (PMID 23077658, 2012).
Bladder tumors (2 papers, 2015 to 2019). "Consistent with our results for human bladder tumours, TYRO3 was the TAM receptor most frequently expressed in UBC cell lines (in 21 out of 25 cell lines), followed by AXL (13/25) and MERTK (7/25)." (PMID 30765874, 2019). "Bladder tumors (NMIBC and MIBC) showed 0.471-fold higher expression of AXL mRNA than control tissues." (PMID 26225770, 2015).
bronchitis (2 papers, 2022 to 2023). An acute or chronic inflammatory process affecting the bronchi. "In another study, pre‐natal tobacco smoke was associated with higher methylation level in the AXL gene in two distinct cohorts, and the combination of higher AXL methylation and PTS exposure at birth increased the risk of recent episodes of bronchitis symptoms in childhood." (PMID 36073598, 2022).
colorectal tumors (2 papers, 2014 to 2022). "Higher mutation frequencies in the RTKs AXL (22%) and EPHA2 (17%) were detected in our panel compared to those reported in the TCGA database for primary colorectal tumors (3.51% AXL and 2.63% EPHA2)." (PMID 25193853, 2014). "Overexpression of AXL in colorectal tumors was reported in metastatic lesions and AXL was recently characterized as a poor prognostic marker in early stage colorectal tumors, and as an important mediator of basal and 5-FU induced EMT and invasiveness." (PMID 25193853, 2014). "Clinically, miR-34 targets showed upregulation in primary colorectal tumors (1–2 fold as compared to healthy colorectal tissue) and their expression was correlated with lymph-node metastases (INHBB, AXL, FGFR1, and PDFGRB) and survival (INHBB and AXL)." (PMID 36429127, 2022).
dengue (2 papers, 2020 to 2025). "Additionally, Spondweni virus also shows AXL dependency, while dengue virus infection is not affected by AXL knockout." (PMID 40062839, 2025).
diabetes (2 papers, 2025). "AXL had many important predicted interactions that may explain its association with diabetes and DN." (PMID 41233312, 2025). "Evaluating the diagnostic power of the parameters under investigation revealed an excellent ability of GAS6 and AXL to differentiate patients with diabetes accompanied by nephropathy from patients with diabetes and normal kidney and from controls, with excellent sensitivity and specificity." (PMID 41233312, 2025). "The gradually decreasing level with diabetes development and DN progression was separately described in Chinese population for GAS6 and AXL." (PMID 41233312, 2025). "However, retinal microglia showed a low but definite expression of AXL in both diabetic and control retina, but no measurable difference accountable to diabetes." (PMID 40940761, 2025). "In contrast to TAM receptor expression in microglial cells, both MerTK and AXL showed a relatively high level of expression in the cortical astrocytes and Muller glia of the retina that was not significantly altered by diabetes, consistent with their role as non-professional phagocytes." (PMID 40940761, 2025).
diabetic nephropathy (2 papers, 2019 to 2020). "Previous studies have shown the controversial effects of Gas6/AXL in several kidney disease models, e.g., anti-Thy-1-induced nephritis, anti-glomerular basement membrane (GBM)-induced nephritis, streptozotocin-induced diabetic nephropathy, and renal ischemia-reperfusion." (PMID 32324796, 2020). "Therefore, the AXL RTK pathway could be relevant for fibrosis development and progression in many different forms of CKD such as diabetic nephropathy." (PMID 31134766, 2019).
diffuse intrinsic pontine glioma (2 papers, 2020 to 2025). A neuroglial tumor that arises from the middle portion of the brain stem. "Additionally, treatment of diffuse intrinsic pontine glioma (DIPG) neurospheres with BGB324 (an AXL inhibitor) in combination with varying doses of 4-Iodo-SAHA (200–500 nM) synergistically reduced DIPG cell viability." (PMID 41496857, 2025).
gastric adenocarcinoma (2 papers, 2020 to 2025). "Based on the AXL RNA-Seq data in gastric adenocarcinoma tissues, the GC patients were divided into a high expression group (n = 188) and a low expression group (n = 187) with a cutoff of 4.80 transcripts per million." (PMID 39644434, 2025). "We further performed survival analyses to assess the prognostic value of MET and AXL in patients with gastric adenocarcinoma." (PMID 34766112, 2020).
glomerular nephritis (2 papers, 2020 to 2023). "A study documented the efficacy of CH5451098, a novel AXL inhibitor, in a mouse model of glomerular nephritis, revealing its potential in ameliorating kidney dysfunction by targeting EMT in tubular cells." (PMID 37813528, 2023). "We employed NEP25 mouse model for exploring the effects of therapeutic interventions of an AXL inhibitor because the model can follow the clinical course of glomerular nephritis followed by tubulointerstitial fibrosis within three weeks." (PMID 32324796, 2020). "Our results using this model which shares the features of the clinical course of glomerulonephritis reveal the importance of AXL in the pathogenesis of renal dysfunction." (PMID 32324796, 2020). "In conclusion, CH5451098 is a highly selective and potent AXL inhibitor that ameliorated kidney dysfunction in glomerular nephritis through the inhibition of EMT." (PMID 32324796, 2020). "Although this suggests that AXL and Gas6 strongly contribute to disease progression of glomerular nephritis, the precise mechanism of AXL in kidney diseases remains unknown." (PMID 32324796, 2020).
helminth infection (2 papers, 2020 to 2021). "In the context of IL-4-inducing helminth infection, genetic ablation of phagocytic receptors, MerTK and AXL, leads to reduced proliferation of macrophages and induction of anti-inflammatory and tissue repair genes." (PMID 33668084, 2021). "The concomitant helminth infection in patients with MS also increased the expression level of AXL in CD1chigh DCs, and notably, there were more cells (%) expressing high levels of AXL in the HIMS group." (PMID 33347509, 2020).
hematoma (2 papers, 2023 to 2025). A hematoma is a collection of blood from a vascular structure into an extravascular space. "In mice, loss of the phagocytic receptor tyrosine kinases AXL and MerTK not only reduced phagocytosis but also decreased alternative activation of macrophages after ICH, which resulted in delayed hematoma clearance and neurological recovery." (PMID 37601043, 2023).
islet cell tumors (2 papers, 2007 to 2021). "Our analysis identified additional genes, including AXL, MFAB, and AXIN2, whose elevated expression in islet cell tumors suggests signal transduction pathways important in their development." (PMID 17389914, 2007).
kidney inflammation (2 papers, 2020 to 2024). "AXL expression is associated with kidney inflammation in humans, while, AXL inhibition has been shown to ameliorate kidney inflammation and fibrosis in several mouse model studies." (PMID 39559366, 2024).
lupus nephritis (2 papers, 2020 to 2023). Glomerulonephritis in the context of systemic lupus erythematosus. "Serum concentrations of this soluble AXL and the Gas6 ligand increase in patients with class 3 or 4 lupus nephritis and are well correlated with the disease activity index." (PMID 32324796, 2020). "AXL is reported to be highly expressed not only in mesangial cells but also in tubular epithelial cells from patients with IgA nephropathy or lupus nephritis, however the function of AXL in damaged tubular epithelial cells is not well understood." (PMID 32324796, 2020). "Similarly, another study showcased the potential of soluble AXL (sAXL) as a marker for assessing renal activity, histological response, and renal damage progression in lupus nephritis." (PMID 37813528, 2023).
meningioma (2 papers, 2023 to 2025). A generally slow growing tumor attached to the dura mater. "Moreover, carbozantinib also inhibits receptor tyrosine kinases AXL and c-MET, which have both previously been shown to demonstrate elevated expression in recurrent meningiomas." (PMID 36672431, 2023).
mesenchymal tumors (2 papers, 2014 to 2023). "On top of that, AXL expression was strongly associated with a mesenchymal phenotype across a panel of 643 human cancer cell lines and ES are mesenchymal tumors." (PMID 25528764, 2014). "AXL overexpression and Kit downregulation were detected in imatinib-resistant gastrointestinal mesenchymal tumors, hence the term ‘‘tyrosine kinase switch’’ was coined for AXL." (PMID 37265798, 2023).
ovarian serous cancer (2 papers, 2019 to 2025). "Tilvestamab, an anti-AXL mAb, demonstrated a tolerable safety profile with limited preliminary antitumor activity in a phase 1 clinical trial of patients with relapsed, platinum-resistant high-grade serous ovarian cancer." (PMID 41166388, 2025). "To determine whether p5RHH nanoparticles could decrease migration and invasion, we first asked whether they could decrease AXL expression in uterine and ovarian serous cancer cells." (PMID 30886159, 2019).
papillary thyroid carcinoma (2 papers, 2022 to 2025). "In this study, the expression levels of AXL/PROS1 were elevated in human papillary thyroid carcinoma." (PMID 36203174, 2022). "Having identified AXL as a tyrosine kinase family with similar attributes, we aimed to explore the PROS1-AXL-mediated TAM signaling pathway for the clinical management and prognosis of papillary thyroid cancer by providing a deeper understanding of its underlying molecular mechanisms." (PMID 36203174, 2022). "This study explores the role of AXL and its ligand PROS1 in the generation and biological behaviour of papillary thyroid cancer (PTC)." (PMID 36203174, 2022).
parasitemia (2 papers, 2022 to 2024). "In addition, it was observed that AXL-deficient macrophages showed better control of parasitic infection." (PMID 38391974, 2024). "Therefore, the correlation between iNOS and AXL may affect the immune response during Trypanosoma cruzi infection, with suppressive activity on the M1 response and a better control of parasitic infection." (PMID 38391974, 2024).
Parkinson disease (2 papers, 2022 to 2024). A progressive degenerative disorder of the central nervous system characterized by loss of dopamine producing neurons in the substantia nigra and the presence of Lewy bodies in the substantia nigra and locus coeruleus. "Consistent with the in vitro observations, only MERTK but not AXL variants were genetically associated with Parkinson’s disease cases in the UKBB cohort." (PMID 37671615, 2024).
periodontitis (2 papers, 2021 to 2025). An acute or chronic inflammatory process that affects the tissues that surround and support the teeth. "In a mouse model of periodontitis induced by P. gingivalis, the loss of MyD88 in TLR signaling significantly reduced the expression of GAS6, AXL, and PROS1." (PMID 34734092, 2021). "Therefore, the Twist/NF-κB pathway will be the focus of our future research on the role of AXL in the inflammatory regulation in periodontitis." (PMID 34734092, 2021). "Supporting these findings, AXL, TYRO3, and GAS6 were the most accurate in differentiating between periodontally healthy/gingivitis and periodontitis, including mild or severe periodontitis (area under the curve [AUC] ranging from 0.72 to 0.89)." (PMID 41187004, 2025). "However, the specific roles of GAS6 and AXL in periodontitis remain unclear." (PMID 34734092, 2021). "However, similar levels of AXL and GAS6 have been detected in human gingival tissues with or without chronic periodontitis using qPCR." (PMID 34734092, 2021).